BRAF (B-Raf proto-oncogene, serine/threonine kinase)
Diseases named in the same sentence as BRAF in open-access papers (continued):
Sharing a sentence is not in itself a finding about the gene and the disease.
melanoma (continued). "In melanoma, patients with mutated BRAF (median OS: 49.0 months) had a good survival trend compared with those with wild-type BRAF (median OS: 33.0 months)." (PMID 35197093, 2022). "Within BRAF-mutant melanomas, the most common activating mutation results from a single amino acid substitution from a valine to a glutamic acid generating the constitutively active mutant BRAFV600E3,4." (PMID 35768444, 2022). "The patient underwent surgical stabilization of the fracture followed by an open biopsy of the suspicious lesion at the fracture site, which revealed malignant melanoma with BRAF V600E mutation." (PMID 35308763, 2022). "Dabrafenib was also a selective inhibitor of BRAF kinase for patients suffering from BRAF-mutated melanoma, advanced non-small cell lung cancer, and anaplastic thyroid cancer harboring the BRAFV600E mutation." (PMID 36246599, 2022). "Recently, we analyzed the expression level of several onco-suppressor miRNAs and their targets in two BRAF-mutated melanoma cell lines." (PMID 35742999, 2022). "As for V600E, BRAF V600K mutation in melanoma promotes a strong activation of the MAPK and ERK pathway, stimulating cell survival and proliferation." (PMID 35160279, 2022). "The majority of the samples with BRAF mutations were from colorectal cancers (approximately 33%) followed by lung adenocarcinoma (19%) and malignant melanoma (17%)." (PMID 35627184, 2022). "Although the BRAF mutation was found in 3 out of 54 canine melanomas studied, it is far less common than reported in the human disease, where it occurs in 40–50% of cases." (PMID 36686160, 2022). "The melanoma genome is the most frequently mutated, with the BRAF mutation present in 40–60% of melanoma cases." (PMID 35684471, 2022). "Activation of the IGF1R–MEK5–Erk5 pathway was also proved to cause resistance to double treatment with BRAF/MEK inhibitors in melanoma cells." (PMID 35565444, 2022). "It is reported that IGF2BP1 accelerated melanoma cell metastasis and target inhibition enhances the effects of BRAF-inhibitor and BRAF-MEK inhibitors in BRAF mutation melanoma." (PMID 35722625, 2022). "For instance, activating mutations at V600 of the BRAF gene is common in several cancers, including approximately 50% of melanoma." (PMID 36588679, 2022). "Trametinib was approved in 2017 for treating unresectable BRAF V600E or V600K mutation melanoma patients." (PMID 36539659, 2022). "This point mutation occurs in 50% ofmalignant melanomas and represents the most frequent mutation of BRAF." (PMID 35677701, 2022). "The most common genetic mutation in melanoma is the V600E/K mutation of the BRAF gene, which appears in almost 50% of cutaneous and 10–20% of mucosal melanomas." (PMID 36844955, 2022). "BRAF mutation testing is routine and it is mandatory for all patients with advanced melanoma, due to its impact on therapeutic decision making." (PMID 35160279, 2022). "Conversely, inhibition of MEK and BRAF in combination has very little impact on Ras/RAF/MEK/ERK signaling in RAS mutant A375 melanoma cells, as activating RAS mutations operate upstream of both MEK and BRAF in this signaling pathway." (PMID 36358868, 2022). "AC>TT, AC>CT, CA>TT, and CA>AT mutations can activate the BRAF oncogene in melanomas; however, data showing the induction of AC or CA photoproducts is limited, and even less is known about the frequency or context of such lesions." (PMID 36704334, 2022). "It is well-established that effective systemic therapy options for advanced cutaneous melanoma have dramatically improved since the introduction of immunotherapy and, in the case of BRAF V600E/K-mutated melanoma, targeted therapy." (PMID 35323326, 2022). "BRAF is one of the most frequently mutated kinases in human cancer, especially melanoma, with activating mutations in BRAF seen in 40–50% of malignancies." (PMID 36291069, 2022). "Of these BRAF-mutated melanomas, up to 80% carry a mutation in the V600E and another 10–20% in the V600K gene." (PMID 35380338, 2022).
melanoma (continued). "A prominent example is the reappearance of large piles of melanoma tumors after therapy resistance occurs to BRAF inhibitors targeting the V600E mutation." (PMID 36139547, 2022). "Hyperactivation ofthis pathway, primarily through gain-of-function mutations in KRASor BRAF, are commonly described in melanoma, thyroid and colorectalcancers." (PMID 35677701, 2022). "Since our co-localization studies showed that UBIAD1 is mostly present in Golgi apparatus in BRAF-mutated melanoma cells, we examined CoQ10 levels after UBIAD1KD in SkMel28 and A375 cells and we found them to be significantly reduced, as expected." (PMID 35255427, 2022). "Activating mutations in the BRAF gene are the most frequent genomic alterations, present in more than half of all melanoma cases." (PMID 35163570, 2022). "Contemporary, it has been reported that mutation in both NRAS and BRAF is linked with poor prognosis in stage IV of melanoma cases." (PMID 36224606, 2022). "KDM5B is a H3K4 demethylase that has been implicated in melanoma resistance to targeted BRAF inhibitor therapies." (PMID 35515106, 2022). "Melanomas have high frequency of mutations that include mutant BRAF, mutant NRAS, mutant neurofibromatosis type 1 (NF1), and the triple wild type." (PMID 35055084, 2022). "Multiple rare V600 mutations have been described in melanoma (V600D/V600R), although evidence is very limited in terms of clinical characteristics and benefits from target therapy with BRAF/MEK inhibitors." (PMID 35160279, 2022). "ACLY was reported to be upregulated in BRAF-mutation melanoma and promoted mitochondrial biogenesis and OXPHOS to support tumor growth and resistance to vemurafenib." (PMID 36686803, 2022). "In that case, the metastatic mucosal lesion would erroneously be identified as a BRAF-mutated mucosal melanoma." (PMID 34142226, 2022). "We compared two biomarker-screening methods, DNA- and protein-based, to assess the BRAF mutation status in a cohort of 90 melanoma samples enriched in SLN with a low TC content." (PMID 35328303, 2022). "And most of these BRAF co-mutations occur in melanoma and lung cancer, but also found in other tumors." (PMID 35912223, 2022). "In their final prediction model, they combined clinical information, deep learning, and extracted nuclei features to predict BRAF mutation status in H&E WSIs of melanoma." (PMID 36551716, 2022). "The newly arisen keywords of top-papers included “high-risk melanoma”, “dacarbazine”, “untreated-melanoma”, “lymph node-positive melanoma”, “regulatory T-cell”, “T-cell exhaustion”, and “BRAF”." (PMID 36698407, 2022). "Resistance to BRAF/MEKi is associated with upregulation of PD-L1 on both melanoma cells and immune cells, a reduction in the ratio of CD8 + T-cell to T-regulatory cells and an increase in T-cell exhaustion markers such as TIM-3 and PD-1." (PMID 35366166, 2022). "We have also confirmed that the molecular mechanism underlying BRAF-inhibitor resistance in these three melanoma models is the aberrant re-activation of Ras/RAF/MEK/ERK signaling, which is consistent with clinical data." (PMID 36358868, 2022). "Adjuvant targeted treatments, such as BRAF and MEK inhibitors, are added to surgical excision in BRAF-mutated metastatic melanomas to maximize treatment effectiveness." (PMID 35684471, 2022). "Trametinib is the first MEK inhibitor to receive FDA approval for the treatment of melanoma with BRAF-V600E mutations." (PMID 35614034, 2022). "The mutated BRAF gene is dominant among melanoma patients, occurring in approximately 50% of cases and rendering a worse prognosis." (PMID 36555289, 2022). "BRAF is the most thoroughly investigated family member owing to the prevalence of mutations in several cancer types, including melanoma and lung cancer." (PMID 35830914, 2022).
melanoma (continued). "BRAFV600 mutations in melanoma are targeted with mutation-specific BRAF inhibitors in combination with MEK inhibitors, which have significantly increased overall survival, but eventually lead to resistance in most cases." (PMID 36230853, 2022). "Together, these data demonstrate that combinations of CDK12 and JNK inhibitors are synthetic lethal for BRAF-mutated melanoma cells." (PMID 36309522, 2022). "More than ~50% of melanoma lesions are characterized by point mutations of BRAF (V-raf murine sarcoma viral oncogene homolog B1), and the most common mutation displayed is a valine to glutamic acid substitution (V600E)." (PMID 36499700, 2022). "Overall, our study indicates that SEMA6A is a crucial player in the biology of BRAF-mut melanoma, with high protein expression being associated with worse prognosis in term of OS and PFS of advanced disease and shorter relapse-free interval of early disease." (PMID 35440004, 2022). "This led to the development of BRAF inhibitors (BRAFi), which are extremely effective in melanoma patients with BRAFV600E mutations." (PMID 36038253, 2022). "Such examples are seen in HER2-positive breast cancers, Philadelphia chromosome in chronic myeloid leukemia, BRAF mutations in melanoma and few other cancer types." (PMID 35955765, 2022). "The expression of BRAF mutated in melanoma cells induced the up-regulation of IL-1α/β, which promoted the expression of PD-L1 in tumor-associated fibroblasts." (PMID 36016960, 2022). "The obtained PROTAC P4B exhibited effective BRAF degradation to inhibit melanoma and colon cancer harboring BRAF mutation." (PMID 35410300, 2022). "Most patients with BRAF—mutated melanoma are treated with BRAFi/MEKi at some point in their therapy." (PMID 35456332, 2022). "A significant number, around 20%, of melanoma patients harboring BRAF V600E mutation show disease progression early after beginning targeted therapy treatment, indicating the presence of intrinsic resistance in a proportion of melanoma cells within the tumor." (PMID 36613518, 2022). "In fact, most of the studies in autophagy and BRAF-mutated melanomas focus on the role of the degradative sub pathway in the acquired resistance, which is restricted to the tumor cell." (PMID 35008395, 2022). "NGS was recently used to reclassify SN and SM from melanomas of Spitzoid features (MSF) after the WHO’s classification of skin tumors proposed elimination of lesions with BRAF and NRAS mutations from the categories of SN and SM." (PMID 35747831, 2022). "More than 90% of the BRAF-activating mutations observed in melanoma are single-nucleotide mutations that convert Val 600 to Glu (BRAFV600E)." (PMID 36091815, 2022). "In fact, a low number of analyses describe the long-term survival of BRAF mutated melanoma patients and the efficacy of second- or third-line therapy." (PMID 35565255, 2022). "Apart from its dual function in melanoma development, autophagy activation underlies drug resistance to BRAF-targeted therapy, whereas its inhibition improves the therapeutic effect." (PMID 36003368, 2022). "The combination of targeted therapy and immunotherapy to treat BRAF-mutated melanoma to improve antitumor immunity and reduce immune-mediated resistance is therefore an attractive potential therapeutic option." (PMID 35492830, 2022). "Despite this huge progress in melanoma therapy, liver metastasis of CM is well documented as predictor of poor response to ICI or targeted therapy of BRAF-mutated melanoma." (PMID 35109875, 2022). "We also analysed cfRNA copies of KPNA2, DTL, BACE2 and DTYMK across different mutational genotypes of melanoma tissue (N = 33 BRAF/NRAS wild‐type, of those N = 4 positive for TERTprom; N = 41 BRAFV600 mutant and N = 25 NRASQ61 mutant melanomas)." (PMID 36320118, 2022). "In this study, CTNNB1 mutations only occurred in BRAF or NRAS mutated melanomas, suggesting a cooperation between MAPK and Wnt/β-catenin signaling pathways." (PMID 36077603, 2022).
melanoma (continued). "BRAF mutations occur in about 40–60% of melanomas and the vast majority are observed within exon 15 (codon 600, namely BRAFV600E)." (PMID 36016960, 2022). "Vemurafenib is a BRAF-inhibitor active against BRAF V600E mutation, which is expressed in approximately 50% of malignant melanoma." (PMID 35804875, 2022). "Melanoma mutations are common in BRAF (50%), NRAS (13.25%), MEK1 (6%), and less commonly KIT (2.6%), CTNNB1 (2%–3%), GNA11 (2%), or GNAQ (1%), highlighting the importance of controlled MAPK signaling for melanocyte homeostasis." (PMID 35574390, 2022). "Given the high frequency of BRAF mutations in primary melanomas, several studies aimed at identifying lncRNAs regulated by the mutant BRAF kinase." (PMID 35159386, 2022). "For example, the CSF-1R inhibitor PXLX3397, in combination with BRAF inhibitor PLX4720, reduced primary and metastatic BRAF-mutated melanoma in a mouse model." (PMID 35053602, 2022). "PTEN loss is more often found in BRAF-mutant than in NRAS-mutant melanoma, a finding compatible with PI3K/AKT pathway activation by NRAS but not BRAF mutations, which need an additional hit." (PMID 36614156, 2022). "In several MAPKi-resistant melanoma cell lines harboring different BRAF or NRAS mutations, the ERK hyperphosphorylation induced by drug withdrawal stimulates the p38-Fra-1-CDKN1A signaling axis, which results in p21 accumulation and proliferative arrest." (PMID 35326630, 2022). "A BRAF inhibitor in combination with ICIs has demonstrated significant clinical efficacy in BRAF mutation melanoma." (PMID 36551302, 2022). "Acquired resistance to BRAF/MEK-targeted therapy occurs in the majority of melanoma patients that harbor BRAF mutated tumors, leading to relapse or progression and the underlying mechanism is unclear in many cases." (PMID 35058553, 2022). "In BRAF-mutated melanomas, targeted combination treatment with BRAF (BRAFi) and MEK inhibitors (MEKi) is effective, leading to responses in 60–70% of patients." (PMID 34837846, 2022). "Striking BRAF inhibitors, including vemurafenib and dabrafenib, are effective in metastatic or advanced BRAF-mutated melanoma patients." (PMID 35401191, 2022). "Regarding the AKT pathway, a decreased activity in in vitro models was associated with the quiescence of melanoma stem-like cell subpopulations, while the overactivation of the pathway was shown to awaken cells from BRAF-induced senescence." (PMID 35565234, 2022). "We employed CRISPR/Cas9 genome engineering to introduce NRAS Q61K, KRAS G13D and MEK1 Q56P mutations into the A375 melanoma cell line with endogenously high expression of BRAF V600E." (PMID 36358868, 2022). "Approximately 60% of all melanoma patients have cancer with an activating BRAF mutation that can be effectively treated with a BRAF inhibitor." (PMID 36551563, 2022). "BRAF mutated melanoma cells were treated with ascorbate alone or in combination with the BRAF inhibitor vemurafenib." (PMID 35406796, 2022). "Results clearly showed that miRatio significantly distinguished BRAF-mutated melanoma patients characterized by DC vs. PD (P < 0.05)." (PMID 36438490, 2022). "BRAF and MEK targeted therapies substantially improved the BRAF mutated patients’ outcomes, and the combination of these targeted inhibitors is currently the gold standard treatment for high-risk resected melanoma patients." (PMID 35684471, 2022). "Consistent with this, we found that CDK12 is constitutively activated in BRAF-mutated melanoma and that its inhibition impairs the expression of long genes with multiple exons, including genes involved in the DNA damage response." (PMID 36309522, 2022). "Subsequent studies further showed that combined dabrafenib and trametinib, compared with BRAF inhibition alone, led to long-term benefits, delayed the emergence of resistance and reduced toxic effects in patients who had melanoma with the BRAF mutation." (PMID 36551302, 2022).
melanoma (continued). "WM1799 cells, a human BRAF V600E mutated melanoma cell line, appeared to tolerate AKT knockout well and showed complete knockout of each isoform based on immunoblotting." (PMID 35158840, 2022). "The BRAF inhibitor (BRAFi) dabrafenib in combination with the MEK inhibitor (MEKi) trametinib was approved for stage III BRAF V600E/K mutated melanoma patients after complete resection of metastases by EMA and Swissmedic in August 2018." (PMID 35336796, 2022). "The first prospective evidence of vemurafenib in NSCLC came from a histology-independent phase 2 basket trial of vemurafenib, 960 mg/oral twice daily, in BRAF V600 mutation-positive non-melanoma cancers." (PMID 36230797, 2022). "Overall, we conclude that UBIAD1 and CoQ10 are significantly expressed during melanoma progression as well as in melanoma cells carrying both BRAF and NRAS mutations." (PMID 35255427, 2022). "Leonard I. Zon group identified SETDB1 as a cooperator of BRAF (V600E) mutation to accelerate melanoma formation." (PMID 36582533, 2022). "Vemurafenib abrogates RAF-MEK-ERK signaling in melanoma cells that harbor BRAF V600E mutations while causing pathway hyperactivation in wildtype melanoma cells." (PMID 35174094, 2022). "Aberrant mitogen-activated protein kinase pathway activation is the predominant pathogenic signalling pathway in melanoma and is usually activated as a result of BRAF and RAS mutations." (PMID 36140259, 2022). "Over 90% of the BRAF mutations in melanoma consist of a single glutamic acid replacement in the kinase domain (V600E)." (PMID 36551688, 2022). "In solid tumors, resistance to MEK inhibitors in human melanomas with BRAF and NRAS mutations is mediated by high OXPHOS activity, which is attenuated by mTORC1/2 inhibitors." (PMID 36612059, 2022). "Here, we focus on the effects of the pan-HDAC inhibitor ITF2357 (Givinostat) in comparison with SAHA (Vorinostat) in melanoma cells bearing BRAF V600E oncogenic mutation." (PMID 36009541, 2022). "Cobimetinib is a highly selective MEK inhibitor that was approved in combination with vemurafenib in 2015 for the treatment of patients with unresectable or metastatic BRAF V600E/V600K-mutated melanoma." (PMID 36358795, 2022). "In melanomas with the BRAF (V600E) mutation that are resistant to BRAF inhibitors, treating tumor cells with C646, a p300 inhibitor, overcame the resistance to BRAF inhibitors." (PMID 36011043, 2022). "The tumor environment in BRAF-mutated melanoma exhibits multiple acquired immunosuppressive features." (PMID 35492830, 2022). "Several research groups noted that BRAF-mutated melanomas present an increased propensity to metastasize to distant sites, being much more invasive than WT melanomas." (PMID 35887633, 2022). "Most melanomas (≈50%) harbour mutations in the kinase BRAF (mostly BRAFV600E) that hyperactivate the mitogen-activated protein kinase (MAPK) pathway (RAS-BRAF-MEK-ERK)." (PMID 35159327, 2022). "This real-world analysis utilizing the nationwide data from multiple reference oncology centers confirms that treatment with second-line BRAFi/MEKi therapy prolongs the survival of advanced/metastatic BRAF-mutated melanoma patients." (PMID 35456332, 2022). "With these innovative controllable CRISPR/Cas9 systems, the authors managed to suppress cell growth, migration, and invasion, and induce apoptosis in the A375 and G361 melanoma cells that harbor the BRAF V600E mutation." (PMID 36139356, 2022). "Specific BRAF and MEK inhibitors are currently used in melanoma therapy to increase survival in BRAF-mutated patients." (PMID 35684471, 2022). "The discovery of oncogenic BRAF mutations in about 50% of advanced melanomas has emerged as central, transforming melanoma therapy." (PMID 36305167, 2022). "Testing for the presence of BRAF V600 mutations is a standard procedure when commencing the treatment of patients with melanoma." (PMID 35159044, 2022).